STAT3 (signal transducer and activator of transcription 3)
Diseases named in the same sentence as STAT3 in open-access papers (continued):
Sharing a sentence is not in itself a finding about the gene and the disease.
tumor (continued). "Although c-Jun transcription factor up-regulation and activation of STAT3 and PERK in the liver of transgenic mice might contribute to tumour development, CHOP expression might reduce tumorigenesis in transgenic mice on BALB/c genetic background." (PMID 24594856, 2014). "We show here that in BCR/ABL+ tumors the absence of STAT3 accelerates tumor growth assigning a tumor suppressing function to STAT3 in this disease." (PMID 24473086, 2014). "Lastly, STAT3 has also been found to regulate the gene for serum amyloid A (SAA), which can interact with and alter the composition of the extracellular matrix to promote tumor initiation and progression." (PMID 24743777, 2014). "Together, these results suggest that exogenous OSM signaling through STAT3 may be a major contributor to the CSC phenotypes of tumors, and implicate the microenvironment as a critical determinant of tumor seeding and recurrence." (PMID 24675570, 2014). "In other words, in this experimental model, the tumor suppressor effects of STAT3 were revealed only in the absence of PTEN expression." (PMID 24995504, 2014). "Furthermore, accumulating evidence suggests that Stat3 plays an important role in up-regulating VEGF gene expression and inducing tumor angiogenesis under both physiological and pathological conditions." (PMID 24416452, 2014). "Since a chronic inflammatory response of the stomach is crucial for tumour development, we tested whether part of the mode of action of WP1066 is to suppress the STAT3-mediated inflammatory response, which normally contributes to tumour progression." (PMID 24804649, 2014). "Taken together, these results indicate that IMQ may activate STAT3 to increase HIF-1α mRNA expression and may stimulate Akt to promote HIF-1α protein synthesis through ROS in tumor cells." (PMID 24658058, 2014). "Collectively, the results of our present study indicate that stilbenoids may affect both EGFR and Stat3 in malignant, EGFR-overexpressing tumor cells." (PMID 25063218, 2014). "In contrast, hepatocytes with STAT3 expression were found to have a significantly higher tumor formation induced by diethylnitrosamine, as compared to hepatocytes with no STAT3 expression." (PMID 24995504, 2014). "The potent anti-tumor activity of YM155, at least in MM, therefore seems to be mediated by the activation of the unfolded protein response and simultaneous abrogation of IL-6/STAT3 signaling." (PMID 25296978, 2014). "In the present study, we used the glucose analog 2-DG and the pharmacological Hsp90 inhibitor 17-AAG, which destabilizes the HIF-1α protein and disrupts STAT3-HIF-1α activation axis, to limit IMQ-induced aerobic glycolysis to enhance the anti-tumor activity of IMQ." (PMID 24658058, 2014). "Thus, to understand the different sensitivity of MDSCs to sunitinib in different mRCC patients, the STAT3 or STAT5 activation status in the MDSCs and expression of cytokines such as GM-CSF in the tumor would need to be investigated." (PMID 25694811, 2014). "Most important, deletion of STAT3 in DCs did not improve the efficacy of prophylactic or therapeutic DC vaccination in the GL26 mouse tumor model." (PMID 24806510, 2014). "Activation of STAT3 and key inflammatory molecules such as nuclear factor kappa-B (NF-κB) induces COX-2 expression which in turn produces prostaglandins, resulting in upregulation of proinflammatory processes that enhance breast carcinogenesis." (PMID 24809702, 2014). "The mechanistic studies further showed that miR-27a-mediated tumor suppressor could be through targeting SGPP1, Smad2 and STAT3." (PMID 25166914, 2014). "Given that STAT3, MAPK, and PI3K signaling have diverse roles in normal development, it is not surprising that gp130 activation may play a paradoxical role in tumor suppression." (PMID 24675570, 2014). "STAT3 knockdown led to the disruption of the microvascular niche which tumor-initiating cells (TICs) and non-tumor initiating cells (non-TICs)depend on." (PMID 25261365, 2014).
tumor (continued). "In this experiment, CA was used at a concentration of 20 μM, as this dose has been shown to suppress STAT3 activation but not inhibit tumor cell viability." (PMID 24738052, 2014). "Activation of Src kinase leads in turn to activation of a variety of downstream signaling pathways such as the Ras/ MAPK pathway, and activation of the Stat3, resulting in cell cycle progression from G2 to M phase and VEGF production, which aids in angiogenesis and tumor growth and invasion." (PMID 25236161, 2014). "Furthermore, elevated levels of activated STAT3 are found in ESFT and RMS tumor tissues as well as cell lines." (PMID 23531921, 2013). "STAT3 is persistently activated in a range of tumours and it is not surprising that STAT3 expression is also detectable in adherent and CD133− cells." (PMID 23219486, 2013). "Furthermore, scoparone treatment suppressed anchorage-independent growth in soft agar and tumor growth of DU145 xenografts in nude mice, concomitant with a reduction in STAT3 phosphorylation." (PMID 24260381, 2013). "Since activation of IL-6/STAT3 axis signaling in cancer stem cells (CSC) enhances proliferation and survival as well as tumor growth in mice, we decided to detect the presence of CSC in HepG2 cells uninfected and infected with HCMV using a tumorsphere formation assay." (PMID 23555719, 2013). "Interestingly, we have further extended this observation to tumor cells and suggested that in the case of tumor-mediated APC modulation, there are two parallel mechanisms for the activation of STAT3, soluble cytokines versus cell:cell contact." (PMID 24073274, 2013). "Association of clinicopathologic features with signal transducer and activator of transcription 3 (STAT3) expression in the primary tumor of alpha-fetoprotein (AFP)-positive and -negative gastric cancers." (PMID 23382965, 2013). "Consequently when STAT3 was activated, WT1 functioned as a tumor suppressor, but when STAT3 was de-activated, WT1 functioned as an oncoprotein." (PMID 23936312, 2013). "The impact of nuclear-STAT3 levels on tumor grade was studied and a significantly greater percentage of nuclear-STAT3 positive tumors are high grade (20%) compared to nuclear STAT3 negative tumors (5%) (p = 0.064)." (PMID 24098947, 2013). "Most importantly, combined STAT3 and p38 inhibition supported a shift from CD14+ monocyte-like cells to CD1a+ DC in metastatic melanoma single-cell suspensions, indicating a potential for improved DC differentiation in the tumor microenvironment." (PMID 24324467, 2013). "Since STAT-3 is known to signal for cell survival and proliferation, the importance of IL-24 mediated STAT-3 activation was tested using STAT-3 inhibitors in IL-24 receptor-positive tumor cells." (PMID 24377906, 2013). "Positive expression of STAT3 protein was significantly associated with Masaoka staging and WHO histological classification (P < 0.05), but not with age, gender, or tumor size." (PMID 23590999, 2013). "The prognostic value of STAT3/pSTAT3Tyr705 expression was also evaluated using univariate analysis, which showed that STAT3 expression, age, gender and tumor size had no prognostic significance for PFS and OS." (PMID 24386409, 2013). "QD-based analysis confirmed that inhibition of pEGFR by erlotinib stimulates phosphorylation of STAT3 in tumor tissues, and that niclosamide specifically blocks erlotinib-induced STAT3 phosphorylation without affecting pEGFR." (PMID 24019973, 2013). "Thus, a number of tumor cell lines triggers PBMC and MΦ to co-secrete an EGFR agonist and a STAT3 activator." (PMID 23597096, 2013). "In the present study, we have extended observations by us and others to confirm a relationship between ZIP6 and STAT3 protein suggesting a STAT3/ZIP6-mediated mechanism for cell rounding and detachment that explains the observed presence of ZIP6 in tumours that spread to lymph nodes." (PMID 23919497, 2013).
tumor (continued). "To further substantiate the importance of B cells with activated Stat3 in stimulating tumor angiogenesis, we performed in vivo Matrigel assays using B cells with or without intact Stat3 signaling." (PMID 23734190, 2013). "In addition, STAT3 up-regulates S100A9 in hematopoietic progenitor cells, which inhibits further differentiation to DCs and retains these cells as MDSCs, leading to tumor tolerance." (PMID 24339824, 2013). "Lastly, in vivo study indicated that LBH589 inhibited tumor growth and metastasis, without discernable adverse effects comparing to control group, with abrogating gankyrin/STAT3/Akt pathway." (PMID 24093956, 2013). "Given the pivotal roles the oncogenic STAT3 and EGFR pathways play in tumor development, we focused primarily on the repertoire of interleukin-6-like STAT3 activators and EGFR agonists secreted by tumor-primed monocytes and MΦ." (PMID 23597096, 2013). "Based on this result, we analyzed VEGF expression in the tumor tissues, and our findings indicated that VEGF expression was elevated in correlation with TILs; increased VEGF expression is also a downstream target of STAT3 activation." (PMID 23379788, 2013). "Stat3 can be phosphorylated by activated EGFR and promote tumor survival in vivo in NSCLC." (PMID 23937717, 2013). "Such a mechanism may partially contribute to the proliferation and growth of tumor cells with an LMP1-induced increase in the nuclear accumulation of EGFR and STAT3." (PMID 24499623, 2013). "Hence, Stat3 status influenced survival of DNA-damaged KSCs, since the absence of Stat3 led to increased apoptosis of bulge region KSCs following treatment with DMBA ultimately leading to reduced number of mutated cells available for clonal expansion during tumor promotion." (PMID 23577258, 2013). "Similarly, inducible deletion of Stat3 prior to each TPA treatment during the tumor promotion stage delayed tumor onset and tumor multiplicity." (PMID 23577258, 2013). "This would suggest that one or both of these two functions in the wild-type virus would make its replication independent of STAT3 levels, unlike the oHSV utilized for this study, suggesting a mechanism for rQNestin34.5 tumor selectivity." (PMID 23936533, 2013). "We have investigated if berberine could inhibit STAT3 activation in NPC cells by exogeneous stimulus, IL-6, which is commonly secreted by inflammatory stroma cells present in tumor microenvironment." (PMID 24380387, 2013). "FOXP3 may propagate crosstalk between tumor cells and their immunological microenvironment, e.g., involving signal transducer and activator of transcription 3 (STAT3), leading to tumor-induced immunosuppression, including the induction of Tregs." (PMID 24649219, 2013). "Results showed that administration of anti-IL-6 mAb but not rat IgG antibody significantly inhibited tumor growth and p-Stat3 expression in wild-type mice." (PMID 24453427, 2013). "Further investigation of the underlying mechanism revealed simvastatin could exert the anti-tumor effects by suppressing IL-6-induced phosphorylation of JAK2 and STAT3." (PMID 23690956, 2013). "Despite an abundance of work focused on the inhibition of Stat3 activation, the anti-tumor effects on NPC have not yet been reported." (PMID 23382914, 2013). "STAT3 plays a central role in MDSC function, promoting tumor invasion, and angiogenesis." (PMID 23508517, 2013). "Results from this set of experiments showed that tumor-primed B cells lacking a functional Stat3 did not effectively support endothelial cells to form tube-like structures." (PMID 23734190, 2013). "Furthermore, STAT3 is aberrantly activated in human CRC tissue and found to correlate to malignant tumor progression through the up-regulated expression of matrix metalloproteinases." (PMID 23385555, 2013). "A positive correlation between p-Stat3 expression and depth of tumor invasion, but not tumor size, was also observed." (PMID 23577258, 2013).
tumor (continued). "Combined inhibition of EGFR and STAT3 by erlotinib and niclosamide more effectively induced apoptosis in tumor tissues without toxicity for normal tissues." (PMID 24019973, 2013). "Many tumor-derived factors, such as IL-10, IL-6 and VEGF that are crucial for both tumor growth and immunosuppression, activate STAT3 to create an efficient “feed-forward” loop to induce persistent STAT3 activity in tumor cells and the tumor microenvironment." (PMID 24324713, 2013). "To study the effects of pardaxin on tumor functions, we performed a real-time RT-PCR analysis of caspase-3, caspase-7, caspase-8, caspase-9, Bax, Bcl-2, STAT2, ATF3, STAT3, SOCS3, IL-2, cathelicidin, TNF-α, MyD88, NF-κB1, p65, IFN-β1, IFN-γ, IL-1β, IL-6, IL-7r, and IL-10." (PMID 23015777, 2012). "We found that at 100 μmol/L (previously reported IC50 of 86 ± 33 μmol/L) S31-201 reduced viability of STAT3 positive ESFT tumour cells, but not of the STAT3 null PC3 cell line." (PMID 22315522, 2012). "We studied whether STAT3 contributes to tumour growth by performing viability assays of cells in growth conditions in a panel of three ESFT cell lines, which harbour constitutively activated STAT3." (PMID 22315522, 2012). "Neither the Stat3 inhibitor nor docetaxel as single agents showed any reduction in tumor volume, relative to vehicle treated controls." (PMID 22879872, 2012). "Phospho-STAT3 was confirmed to be reduced in tumor cells of the vehicle- treated mice, but not in stromal cells, while tumor- and stromal- phospho-STAT3 were significantly reduced in AZD1480- treated mice (Fig. 4C2)." (PMID 23056499, 2012). "We show that high levels of IFN-γ are produced during aATC-mediated targeted killing of tumor cells, thus we reasoned that IFN-γ may induce apoptosis by inhibiting Stat3 phosphorylation and inducing Stat1 phosphorylation." (PMID 23185240, 2012). "In our recent study, we found that MSM suppresses tumor growth via inhibition of the STAT3 and STAT5b pathways, while being non-toxic to normal cell line MCF-10A." (PMID 23071812, 2012). "This inhibitor was designed to block Stat3 but not Stat1 function, thereby presumably avoiding the tumor antagonist effects of Stat1." (PMID 22838736, 2012). "STAT3 activation can upregulate the expression of anti-apoptotic proteins (Bcl-2, Mcl-1 and Bcl-x), proliferation related proteins (cyclin D1 and c-Myc) and angiogenesis promoting factors (VEGF) to prevent tumor cells from apoptosis." (PMID 23554768, 2012). "Thus, suppressing the activation of STAT3 by physical (i.e., HIFU) or pharmacological approaches is of great interest for both direct anti-tumor treatment and tumor specific immunotherapy." (PMID 22911830, 2012). "Moreover, EP significantly suppressed the growth of U266 cells inoculated in female BALB/c athymic nude mice and immunohistochemistry revealed that EP effectively reduced the expression of STAT3 and CD34 in tumor sections compared to untreated control." (PMID 22260501, 2012). "The lack of increased angiogenesis as reflected by CD31 count and tumor hypoxia as reflected by CA9 expression, in the setting of treatment failure of cediranib, was contrasted by a statistically significant increase in p-STAT3 expressing macrophages." (PMID 23013619, 2012). "In addition to biochemical and molecular data linking APE1 and STAT3 in PDAC cells, our studies reveal potent anti-tumor synergism of the combination of APE1 redox inhibition and STAT3 blockade." (PMID 23094050, 2012). "Therefore, using inhibitors that target two critical proteins, APE1 and STAT3, we can potentially disable multiple key pathways in PDAC cell survival, and to disrupt the integration of signals between tumor and the microenvironment." (PMID 23094050, 2012). "Cucurbitacin E also suppressed tumor angiogenesis through interacting vascular-endothelial-growth-factor-receptor-2-(VEGFR2-) mediated Janus kinase 2 (Jak2)-signal transducer and activator of transcription 3 (STAT3) signals." (PMID 22272214, 2012).
tumor (continued). "STAT3 and STAT6 are involved in inhibiting anti-tumour immunity." (PMID 21694723, 2011). "In addition, we also detected the Y705 phosphorylated form of STAT3 and found increased amounts of this phosphorylated form of STAT3 in GBM in comparison to non-tumour tissue and ODG." (PMID 21655185, 2011). "Thus, by trapping active STAT3 within the cytoplasm, STAT3-decoy ODN can simultaneously trap the fraction of NF-κB that is associated to active STAT3; this may potentially allow the targeting of a subset of genes that is essential for uncontrolled tumor cell growth." (PMID 21486470, 2011). "In conclusion, our results suggested that the IL-17 mediated tumor-promoting role involved a direct effect on tumor cells through IL-6 induction by activating the AKT pathway; IL-6 in turn activated JAK2/STAT3 and up-regulated proinvasive factors IL-8, MMP2, and VEGF both in vitro and in vivo." (PMID 22171994, 2011). "For the reciprocal regulation of STAT1/3 activity, STAT3 inhibition by JAK/STAT antagonist AG490 may allow STAT1 activation and the expression of antitumor cytokines to suppress tumor metastasis." (PMID 21931823, 2011). "However, other pathways are operative in this patient's tumor, including Ras/Raf /ERK and STAT3.The relative overexpression of CD99 in this patient is consistent with activation of this pathway (not shown)." (PMID 21494688, 2011). "Similarly, it was found that in vivo inactivation of genes that govern MDSCs accumulation, such as STAT3 and STAT6 restores T cell function and promotes tumor regression." (PMID 21943203, 2011). "Moreover, constitutive activation of STAT-3 occurs at a frequency of 50–90% in a broad range of human cancers, suggesting that STAT-3 activity contributes significantly to tumor VEGF overproduction." (PMID 22016776, 2011). "Cell proliferation was comparable between HCC cells only and tumor cells treated with or without IL-6 antibody or STAT3 inhibitor." (PMID 22136659, 2011). "For example, although inhibiting STAT3 may overcome some of the immunosuppressive mechanisms employed by GBM, immune cells must still efficiently identify appropriate tumor-specific antigens in order to avoid immune editing." (PMID 22190972, 2011). "Finally, known tumor-promoting downstream effectors of JNK1 and STAT3 displayed enhanced expression (e.g., Myc, Jun, Mmp9, and Vegfa), which was restricted to DKO livers." (PMID 21725989, 2011). "Constitutive Stat3 phosphorylation has been found in several solid tumors and hematologic malignancies, and it is likely that ROR1 will be detected in these neoplasms as well." (PMID 20686606, 2010). "We hypothesized that suppression of both B-Raf/Mek/Erk/Stat3 and NF-κB signaling through combined administration of ATRA and ACA/AUR, may exert a stronger anti-tumor effect than either agent alone." (PMID 20659317, 2010). "The pro-oncogenic transcription factor STAT3 is constitutively activated in a wide variety of tumours that often become addicted to its activity, but no unifying view of a core function determining this widespread STAT3-dependence has yet emerged." (PMID 21084727, 2010). "Many downstream signaling effectors involved in malignancy are regulated by both Stat3 and NF-κB, such that targeting both of these signaling pathways at once by combining ATRA + AUR, may produce a synergistic tumor suppressive effect." (PMID 20659317, 2010). "In TMV-treated Treg, increased expression levels of phospho-STAT3 and phospho-SMAD2/3 and of IL-10 and TGF-β1 expression as well as production may be responsible for attenuating anti-tumor immune responses in cancer patients." (PMID 20661468, 2010). "Phosphorylated-Stat3 was expressed only in the nuclei of the tumour cells and was not expressed in the nuclei or cytoplasm of normal cells." (PMID 19638983, 2009).